IFI30 (IFI30 lysosomal thiol reductase)
Diseases named in the same sentence as IFI30 in open-access papers (continued):
Sharing a sentence is not in itself a finding about the gene and the disease.
lung carcinoma (2 papers, 2019 to 2023). "Our results in line with these findings suggest that lung cancer cell secreted IFI30 promotes inflammatory response observed in co-culture scenario." (PMID 37784035, 2023). "In this study, we have demonstrated that the lung cancer cell-monocyte cross-talk modulates the secretion of IFI30, RNH1, CLEC3B, VCAN, IGFBP2, C2 and TUBB4B favoring tumor growth and metastasis." (PMID 37784035, 2023). "In conclusion, this study identifies IFI30, RNH1 and CLEC3B, VCAN, IGFBP2, C2, TUBB4B as the proteins secreted by lung carcinoma cells and monocytes respectively as a result of their mutual interaction." (PMID 37784035, 2023).
atherosclerosis (1 paper, 2012). A disease characterized by the build-up of fatty material and calcium deposition in the arterial wall resulting in partial or complete occlusion of the arterial lumen. "Interferon, gamma-inducible protein 30 (IFI30) (FC+23.2) demonstrated high expression and it has not been previously identified in atherosclerosis." (PMID 22509262, 2012). "Since both IL41I, and IFI30 participate in the down-regulation of Th1 mediated inflammation, a crucial element in atherosclerosis, our results of high expression of IL41I and IFI30 may reflect a negative feedback response to Th1 mediated inflammation in the atherosclerotic process." (PMID 22509262, 2012).
brucellosis (1 paper, 2024). Brucellosis is a bacterial infection that spreads from animals to people via unpasteurized dairy products or by exposure to contaminated animal products or infected animals. "In brucellosis patients, the expression levels of many typical IFN‐γ/IFN‐I response genes, including IFITM3, B2M, GBP1, IRF1, IFI30, IFNGR2, and so forth, were higher than those in controls." (PMID 39135683, 2024).
cervical cancer (1 paper, 2022). A primary or metastatic malignant neoplasm involving the cervix. "Consistently, the expressions of IGSF6, TLR10, FCRL3, and IFI30 were upregulated in cervical cancer in the validation cohort." (PMID 36387234, 2022). "Apart from this, an intriguing notion is that the four genes (IGSF6, TLR10, FCRL3, and IFI30) were also upregulated in cervical cancer compared to normal tissues, while their high expressions predicted better prognosis." (PMID 36387234, 2022). "In line with the results from the transcriptomics, we identified stronger expressions of IGSF6, TLR10, FCRL3, and IFI30 in cervical cancer tissues compared to normal tissues." (PMID 36387234, 2022). "To validate the expressions of IGSF6, TLR10, FCRL3, and IFI30 in cervical cancer, we performed immunohistochemistry against these genes, respectively." (PMID 36387234, 2022). "As the expressions of IGSF6, TLR10, FCRL3, and IFI30 were all upregulated in cervical cancer and the higher expressions of IGSF6, FCRL3, and IFI30 predicted better prognosis, we asked if the combination of these four genes was associated with the risks of cervical cancer." (PMID 36387234, 2022). "Based on these facts, we thought that the discovery of the 4 novel genes (IGSF6, TLR10, FCRL3, and IFI30) in cervical cancer might shed light on the clinical treatments of cervical cancer as well." (PMID 36387234, 2022). "By univariant Cox and LASSO analyses, we finally got 4 genes (IGSF6, TLR10, FCRL3, and IFI30) that were closely correlated with both the CD8+ T cell infiltration and the prognosis of cervical cancer." (PMID 36387234, 2022). "To validate the immune infiltration pattern, the expressions of IGSF6, TLR10, FCRL3, and IFI30, and the correlation between them, we downloaded the GSE151666 dataset from the GEO database as a validation cohort, which included 68 cervical cancer patients." (PMID 36387234, 2022).
clear cell renal cell carcinoma (1 paper, 2024). "Although the immune factor interferon gamma-inducible protein 30 (IFI30) has been linked to the growth and immune infiltration of various malignancies, its function and mechanism in clear cell renal cell carcinoma (ccRCC) remains unclear." (PMID 37991414, 2024).
developmental delay (1 paper, 2022). "Meanwhile, loss of Ifi30-caused developmental delay was excluded by further observation." (PMID 35910561, 2022). "Moreover, the defective vasculature caused by loss of Ifi30 was not a result of developmental delay." (PMID 35910561, 2022).
glaucoma (1 paper, 2025). Increased pressure in the eyeball due to obstruction of the outflow of aqueous humor. "Additionally, PPI network analysis showed that IRF1, IFI30, NR3C1 and LRRC14 have relatively abundant interacting proteins, suggesting that these genes might act as key regulatory nodes in the molecular pathways underlying HBP and glaucoma." (PMID 41170525, 2025). "The number of interacting proteins for IRF1, IFI30, NR3C1 and LRRC14 was relatively abundant, suggesting that they may play a key role in the regulatory pathways of HBP and glaucoma." (PMID 41170525, 2025).
low grade glioma (1 paper, 2022). A grade I or grade II glioma arising from the central nervous system. "They found that the level of IFI30 was higher in GBM specimens than in low-grade glioma (LGG) specimens." (PMID 35436915, 2022).
mastitis (1 paper, 2018). Inflammation of breast tissue during lactation or postpartum due to an obstructed duct or infection. "The SNP rs41255569 on BTA7, an upstream gene variant and in significant association with susceptibility to mastitis in parity 3, is mapped very near to a functionally known candidate genes MAST3 (microtubule associated serine/threonine kinase 3) and IFI30 (lysosomal thiol reductase)." (PMID 29755506, 2018).
multiple sclerosis (1 paper, 2021). A progressive autoimmune disorder affecting the central nervous system resulting in demyelination. "IFI30 plays a crucial role in MHC class II-restricted antigen processing, and its expression is greatly enhanced on microglia in active demyelinating lesions of multiple sclerosis." (PMID 33958982, 2021).
myositis (1 paper, 2024). "In terms of myositis, marker genes encoding lysosomal proteins including cathepsins (CTSA, CTSK), IFI30 Lysosomal Thiol Reductase (IFI30) and CD74 Molecule (CD74) suggested active lysosome and immune cells activities in muscle turnover." (PMID 38342952, 2024).
steatosis (1 paper, 2024). Increased lipid within the cytoplasm of cells. "CD63, C-Type Lectin Domain Family 1 Member B (CLECB1), CD38, MANF, and Gamma-interferon-inducible lysosomal thiol reductase (IFI30) were all associated with steatosis grade in PWS." (PMID 39407757, 2024).
tumor (38 papers, 2009 to 2026). "Overexpression of CD74, CLEC7A, and IFI30 in macrophages further enhanced M2 polarization, which was associated with increased tumor-promoting functions, including enhanced invasion and reduced apoptosis in GBM cells." (PMID 41892299, 2026). "Overall, these findings highlight IFI30 as a diagnostic and prognostic marker, as well as its potential role as a tumor‐promoting factor in ESCC progression." (PMID 40186402, 2025). "Beyond its well‐established immunological function, IFI30 has been implicated in tumor initiation and progression, reactive oxygen species (ROS) generation, and autophagy activation, making it a potential target for cancer therapy." (PMID 40186402, 2025). "Further analysis using the UALCAN database revealed that higher IFI30 mRNA expression was associated with advanced cancer stages and higher tumor grades in ESCA." (PMID 40186402, 2025). "We found that IFI30 expression was higher in ccRCC tissues compared to normal tissues and was strongly associated with tumor grade, T stage, and M stage." (PMID 37991414, 2024). "We utilized data from the TCGA and Tumor Immune Estimation Resource (TIMER) databases to investigate the association between IFI30 expression and immune cell infiltration." (PMID 37991414, 2024). "Although IFI30 mainly participates in antigen processing and immune responses, it is also highly associated with tumor progression and angiogenesis." (PMID 35910561, 2022). "GILT, the protein encoded by IFI30, was shown to enhance the T cells mediated immune surveillance against tumor cells, implying its druggable potential in tumor therapy." (PMID 36387234, 2022). "We further examined the significance of IFI30 as a prognostic as well as diagnostic marker in tumour patients by incorporating the TCGA along with the GTEX database and the results were presented in the format of univariate Cox regression analysis and Kaplan-Meier survival analysis." (PMID 39925804, 2025). "In addition, studies on the tumor microenvironment show that increased infiltration of M2-type macrophages was associated with high IFI30 expression." (PMID 37784035, 2023). "We then further targeted the immunomodulatory pathways within the GO-BP pathway and found that the changes in the expression of IFI30 are correlated with several key indicators and pathways in the tumor immune process." (PMID 39925804, 2025). "As anticipated, the results demonstrated that nude mice with IFI30 knockdown exhibited significantly reduced tumor volume and weight compared to controls." (PMID 40186402, 2025). "The tumor growth curve demonstrated that IFI30 knockdown inhibited tumor growth, which became more evident with time." (PMID 40186402, 2025). "These discrepancies likely reflect the tumor‐type‐specific regulation of downstream targets and signaling pathways by IFI30, underscoring the necessity for cancer‐specific investigations." (PMID 40186402, 2025). "Our approach involves a multi-omics analysis of IFI30 tumor immunological profile in the macrophage-mediated Tumor Microenvironment (TME), spanning various cancers and bolstered by rigorous co-culture laboratory work." (PMID 39925804, 2025). "Functional assays revealed that knockdown of IFI30 significantly inhibited cell proliferation, migration, and invasion, and in vivo experiments showed that IFI30 knockdown markedly suppressed tumor growth." (PMID 40186402, 2025). "In contrast, the downregulation of TGF‐β and MMP‐9 is associated with inhibited matrix remodeling and invasiveness, which aligns with our functional experiments demonstrating that IFI30 knockdown contributes to tumor suppression." (PMID 40186402, 2025). "Although it cannot yet be fully confirmed that IFI30 has a significant causal impact, it has provided valuable clues and potential research directions for the subsequent in-depth exploration of the specific mechanism of IFI30’s role in tumor immunity." (PMID 39925804, 2025).
tumor (continued). "Additionally, our investigation into immune-infiltrating T cells revealed a strong correlation between IFI30 expression level and the infiltration of T cells, helper T cells, and Tcm cells, indicating that IFI30 may have a regulating function in tumor-associated macrophage (TAM) polarization." (PMID 37991414, 2024). "Overexpression of IFI30 significantly increased the tumor volume compared with that in the control group." (PMID 37408388, 2023). "In recent years, multitudes of scholars extended this to the direction of tumor immunity, thus revealing the great potential of IFI30 in the tumor immune microenvironment." (PMID 37215115, 2023). "Modulation of IFI30 expression to break off the pathway for MHC-restricted tumor antigen presentation has been proven to contribute to malignant cells evading T-cell surveillance of the immune system." (PMID 37065491, 2023). "As shown, overexpression of IFI30 significantly increased tumor volume and weight compared with that in the control and AG‐1478 groups." (PMID 37408388, 2023). "As shown, knockdown of IFI30 significantly reduced tumor volume and weight compared with those in the control group." (PMID 37408388, 2023). "These malignancies are generally characterized by a high metastatic trait and strongly correlated with neovascularization, suggesting a potential role of IFI30 in promoting tumor angiogenesis and cell proliferation." (PMID 35910561, 2022). "Tumor production curves revealed that knockdown of IFI30 resulted in inhibition of tumor growth, which was more pronounced with time, and mice with IFI30 knockdown had significantly less tumor weight than the controls." (PMID 34400904, 2021). "To further investigate the role of IFI30 in vivo, we performed tumor bearing experiments in nude mice and obtained the same results." (PMID 34400904, 2021). "Next, we compared the specificity and sensitivity of IFI30 expression, the patient age at diagnosis, and the tumour grade in predicting OS." (PMID 32969157, 2020). "Since proteins are the functional executors of gene expression, we performed proteomic analysis on 82 pairs of ESCC tissues and adjacent non‐cancerous tissues and found that IFI30 protein expression was significantly higher in ESCC tissues than in paired non‐tumor tissues." (PMID 40186402, 2025). "More than this, we initially identified the possible role of IFI30 in tumor immunotherapy by systematic and large-scale pan-cancer GSEA analysis, and validated this conclusion by multiple immune assessment algorithms and correlation analysis of tumor immune micro environment (TIME) features." (PMID 39925804, 2025). "According to the original article we could infer that the expression of IFI30 was mainly located in the central tumor location." (PMID 39925804, 2025). "Recent studies have highlighted the therapeutic potential of targeting IFI30 in anti-tumor strategies, suggesting that modulating its expression or activity could regulate the immune response against tumor cells." (PMID 39308856, 2024). "The potential functions and mechanisms of IFI30 were examined by public dataset analysis; quantitative real‐time PCR; WB; limiting dilution analysis; xenograft tumor assays; CCK‐8, colony formation, wound healing, and transwell assays; and immunofluorescence microscopy and flow cytometry." (PMID 37408388, 2023). "In addition, in vivo and in vitro studies showed that IFI30 silencing suppressed tumor progression and enhanced the therapeutic effect of TMZ treatment." (PMID 37408388, 2023). "IFI30 is considered to be a typical regulating immune regulator belonging to the γ-interferon stimulated gene family, responsible for the activation of tumor progression." (PMID 35436915, 2022). "Higher levels of autophagic events in tumor cells may also promote lysosomal degradation where IFI30 can influence protein processing by other acidic proteases such as cathepsins." (PMID 34400904, 2021).
tumor (continued). "Part of the studies suggested that IFI30 acted as a tumor suppressor in some tumors." (PMID 34400904, 2021). "IFI30 knockdown in ESCC inhibited cell proliferation, migration, and invasion in vitro and suppressed tumor growth in vivo." (PMID 40186402, 2025). "For instance, in the context of melanoma, IFI30 has been demonstrated to potentiate the processing and presentation of tumour antigens, TRP1 and TRP2, consequentially augmenting anti-tumour T cell responses and culminating in enhanced patient survival rates." (PMID 39925804, 2025). "IFI30 knockdown inhibited ESCC cell proliferation, migration, and invasion in vitro and suppressed tumor growth in vivo." (PMID 40186402, 2025). "Based on the argument that tumor-infiltrating immune cells in TME take an influential role in cancer progression, we further analyzed the infiltration of IFI30 with a variety of immune cells." (PMID 39925804, 2025). "CTSZ, IFI30, CXCL8).Tumor NK cells were enriched for the d2 and d3 dog NK subclusters, classified by signaling and regulation, respectively." (PMID 41208961, 2025). "Knockdown of IFI30 in ESCC inhibits cell proliferation, migration, and invasion in vitro, as well as tumor growth in vivo." (PMID 40186402, 2025). "IFI30, OASL, and a HSP70 were found to be upregulated in tumor samples as observed in the proteomic analysis." (PMID 30651403, 2019). "Similar profile is seen in genes expressed in HCCN vs. HCV+HCC (tumor state): PCNA-AS1, ROBO1, DAB2, and IFI30 (lower part)." (PMID 28938650, 2017). "As for KIRC, the expression of IFI30 in tumor samples is significantly higher than that in non-tumor samples, both in paired and non-paired samples." (PMID 38517387, 2024). "Further, we detected several genes that were both mutated and differentially spliced in the same cell types, such as HMGN3 and UBE2G2 in tumor cells, CD74 and IFI30 in myeloid cells, and RPS2 in endothelial cells indicating their important roles in tumorigenicity." (PMID 37433798, 2023). "The expressions of IFI30 and TGFBI in tumor and normal tissues were verified by THPA database." (PMID 35634956, 2022). "IFI30 is constitutively expressed in professional antigen-presenting cells (APCs), including B cells, dendritic cells and monocytes/macrophages, and induced by interferon-γ (IFN-γ) in other cell types, such as tumor cells." (PMID 35910561, 2022). "In fact, studies have reported that IFI30 and HLA-DMA could be related to immune response process which play tumor-regulatory roles in GBM." (PMID 35436915, 2022). "The data again emphasize key differences between cell lines and primary tumors and that future functional studies, such as RNA silencing or over-expression of IFI30, GPB1, and GBP4 should be performed in primary tumors to evaluate the function of such factors in the tumor microenvironment context." (PMID 32265897, 2020). "Moreover, the newly induced SASP characteristics by IFI30 knockdown, including elevated levels of IL‐6, IL‐8, and TNF‐α, as well as decreased levels of TGF‐β and MMP‐9, reflect the dynamic interplay between senescence and tumor suppression." (PMID 40186402, 2025). "Targeting IFI30 could confer several advantages, including inhibiting tumor progression by inducing cell apoptosis and senescence, enhancing chemotherapy sensitivity (such as promoting DDP‐induced apoptosis), and remodeling the tumor microenvironment (such as reprogramming the SASP)." (PMID 40186402, 2025). "IFI30, GBP1 and GBP4 were upregulated 2-8-fold (p < 0.0001) in IFNγ positive tumors vs. IFNγ negative tumors in each of the six tumor types." (PMID 32265897, 2020).